CTLA4 (cytotoxic T-lymphocyte associated protein 4)
Diseases named in the same sentence as CTLA4 in open-access papers (continued):
Sharing a sentence is not in itself a finding about the gene and the disease.
lung fibrosis (6 papers, 2010 to 2025). "In this report, we demonstrate that the immune checkpoint protein, cytotoxic T lymphocyte–associated protein 4 (CTLA4), was markedly upregulated in the lungs of humans with idiopathic pulmonary fibrosis (IPF)." (PMID 40100323, 2025). "In a recent study, anti-CTLA-4 antibody treatment was however shown to aggravate fibrosis in a humanized model of pulmonary fibrosis." (PMID 31561518, 2019). "This claim is however based on a single mouse study and further studies are needed to firmly establish the role of CTLA-4 in pulmonary fibrosis." (PMID 31561518, 2019). "Few studies explored the role of CTLA-4 in pulmonary fibrosis but already over a decade ago CTLA-4 was shown to be overexpressed in IPF lungs as compared to Hypersensitivity Pneumonitis lungs." (PMID 31561518, 2019). "While the reciprocal antagonistic relationship between regenerative capacity of the alveolar epithelium and lung fibrosis is well appreciated, our studies demonstrate a proregenerative effect of targeting CTLA4 and activating cytotoxic T cells during the fibrotic phase of lung injury repair." (PMID 40100323, 2025). "Interestingly, anti-CTLA-4 or anti-PD-1 mAb intervention significantly exuberated the severity of pulmonary fibrosis in humanized NSG mice." (PMID 36544757, 2022). "In pre-clinical models of SSc, T-cell costimulation blockade with abatacept (CTLA-4-Ig) prevented and induced the regression of inflammation-driven dermal fibrosis, improved digestive involvement, prevented lung fibrosis, and attenuated pulmonary hypertension in complementary models of SSc." (PMID 30619351, 2018). "Therefore, IPF CD28null T cells may serve as a profibrotic component in lung fibrosis, but the immune checkpoint molecules CTLA-4 and PD-1 appear to limit this effect." (PMID 36544757, 2022). "The Flow Cytometry and realtime PCR study show that Treg cells exert the modulation function both directly by expressing CTLA-4 at the inflammatory stage, and indirectly by secreting increasing amount of IL-10 and TGF-β during the fibrotic stage in silica-induced lung fibrosis." (PMID 21072213, 2010). "It thus seems that CTLA-4 might play a detrimental role in pulmonary fibrosis and that targeting CTLA-4 in IPF patients is not an interesting option to pursue." (PMID 31561518, 2019).
malignant mesothelioma (6 papers, 2019 to 2025). A malignant neoplasm of the pleura or peritoneum, arising from mesothelial cells. "When patients with malignant mesothelioma were treated with ipilimumab (cytotoxic T lymphocyte-associated antigen-4, CTLA-4 inhibitor) and nivolumab (programmed death 1 blocker, PD-1 inhibitor) in combination with UV1, they recovered more rapidly, eliciting immediate immune responses." (PMID 40563586, 2025). "Immunotherapy based on two checkpoint inhibitors (ICI), programmed cell death 1 (PD-1, Nivolumab) and cytotoxic T-lymphocyte 4 (CTLA-4, Ipilimumab), has provided a significant improvement in overall survival for malignant mesothelioma (MM)." (PMID 34199066, 2021). "However, recent findings indicate that improved survival highly correlates with the frequency of DNAM-1+CD56dim NK and NKp46+CD56dim NK cells after treatment with anti-CTLA-4 in patients with malignant mesothelioma." (PMID 31681269, 2019).
medulloblastoma (6 papers, 2020 to 2026). A malignant, invasive embryonal neoplasm arising from the cerebellum. "We also examined the association between our risk score model and immune checkpoint pathways, focusing on PD-L1 and cytotoxic T-lymphocyte associated protein 4 (CTLA4) since inhibitors targeting these checkpoints have been proposed to be effective in treating medulloblastoma animal models." (PMID 32508873, 2020). "For medulloblastomas, expression analysis from 2 different data sets, representing 4 different subtypes, exhibited variation in expression of PD-L1 and CTLA-4 among subtypes of the disease." (PMID 41541220, 2026). "However, in medulloblastoma alone, the combination of nivolumab with ipilumumab (anti-CTLA-4) demonstrated a trend toward improved overall survival." (PMID 41456573, 2026). "We could corroborate in this large dataset of 763 medulloblastomas the low levels of PDCD1 (PD-1), CD274 (PD-L1), and CTLA4." (PMID 36825029, 2023). "However, it is possible that CTLA-4 based therapies may be more effective in medulloblastoma and that future combination trials should consider CTLA-4 as a backbone rather than PD-1." (PMID 41456573, 2026). "We found that canonical immune checkpoints, such as CTLA4, PDCD1 (PD1), and CD274 (PD‐L1), are absent or exhibit a very low mRNA expression in the medulloblastoma, dpHGG, and PDX." (PMID 40880425, 2025).
metastatic prostate carcinoma (6 papers, 2019 to 2023). A carcinoma that arises from the prostate gland and has spread to other anatomic sites. "Only one report found CTLA-4 expression in CTCs in metastatic prostate cancer (mPC), which was rare." (PMID 36902476, 2023). "Patients and Methods: We evaluated the efficacy of the CTLA-4 targeted agent, ipilimumab, in metastatic prostate cancer patients who had an incomplete biochemical response to initial androgen deprivation therapy (ADT) alone." (PMID 32850444, 2020). "In a large phase III trial with patients with metastatic prostate cancer, no benefit of cytotoxic T-lymphocyte-associated antigen-4 (CTLA-4) blockade after radiotherapy was observed." (PMID 31703637, 2019). "This trial demonstrated that ipilimumab (anti-CTLA4 antibody) plus to a conservative dose of palliative bone-directed RT (8 Gy × 1), which did not improve overall survival (OS) in heavily pre-treated metastatic prostate cancer patients, however treatment was tolerable." (PMID 31105877, 2019).
Myasthenia (6 papers, 2020 to 2025). "Unusually, myasthenia also has a higher reported incidence in anti-PD-1/PD-L1 ICIs compared to anti-CTLA-4 (ROR 3.9)." (PMID 38345654, 2024).
nephritis (6 papers, 2013 to 2025). Inflammation of renal tissue. "For serious nephritis, our study adds new evidence by reinforcing anti-CTLA-4 as the worst treatment class and atezolizumab as the worst single ICI." (PMID 38372756, 2024). "Although the mice treated with high-dose CTLA4-Ig eventually died of nephritis, this treatment markedly delayed proteinuria onset and protected the mice from interstitial inflammation." (PMID 24106491, 2013). "Triple therapy with cyclophosphamide (CTX), anti-CD40L, and CTLA4-Ig induces remission in a high percentage of NZB/W F1 mice with established nephritis." (PMID 24106491, 2013). "Our research identified high expressions of PD1, CTLA4, TIM3, and TIGIT on T cells were correlated with disease activity, nephritis, and treatment response downregulation in SLE." (PMID 38650001, 2024). "In contrast, CTLA4-Ig at standard-dose failed to prevent or delay the onset of nephritis in Ad-IFNα treated mice despite preventing T and B cell activation, GC formation, and the production of pathogenic IgG2a anti-dsDNA antibodies." (PMID 24106491, 2013).
systemic sclerosis (6 papers, 2013 to 2022). A chronic disorder, possibly autoimmune, marked by excessive production of collagen which results in hardening and thickening of body tissues. "Interestingly, autologous hematopoietic stem cell transplantation which led to increase in the number of T-regs (along with higher expression of CTLA-4 and GITR on Tregs) resulted in clinical improvement in systemic sclerosis patients." (PMID 36189219, 2022).
T-cell lymphoma (6 papers, 2015 to 2024). "In this case-control study, we investigated the association between several genetic variants of immunoregulatory genes (IL-10, TNF/LTA, and CTLA-4) and risk for nasal NK/T-cell lymphoma in a Chinese population." (PMID 26108796, 2015). "Clinical trials on the efficacy in T-Cell lymphoma are rare, but one case report reports a rapid clinical response with the CTLA4 inhibitor ipilimumab in a patient with Sezary syndrome harboring a highly expressed gene fusion between CTLA4 and CD28." (PMID 35330161, 2022). "CTLA4 expression is noted in a variety of T-cell lymphomas, namely, peripheral T-cell lymphomas and mycosis fungoides/Sézary syndrome." (PMID 29564225, 2018). "No statistical difference was observed between IL-10 and CTLA-4 haplotypes and NK/T-cell lymphomas." (PMID 26108796, 2015).
teratoma (6 papers, 2019 to 2025). A non-seminomatous germ cell tumor characterized by the presence of various tissues which correspond to the different germinal layers (endoderm, mesoderm, and ectoderm). "A small subset of both germinomas and NGGCTs (8.06%, 5/62, and 9.68%, 3/31, respectively) exhibited minimal T cell infiltration and low expression of immune checkpoints (CTLA-4, PD-1, and PD-L1); these NGGCTs were primarily teratomas or tumors with predominant teratoma components." (PMID 39958339, 2025).
adenoma (5 papers, 2019 to 2025). A neoplasm arising from the epithelium. "To assess therapeutic potential, we engineer EcN to locally release a cytokine, GM-CSF, and blocking nanobodies against PD-L1 and CTLA-4 at the neoplastic site, and demonstrate that oral delivery of this strain reduces adenoma burden by ~50%." (PMID 38245513, 2024). "High CTLA-4 epithelial expression was significantly in favour of adenocarcinoma (p ˂ 0.001), adenoma with high-grade dysplasia (p value ˂ 0.001) and adenoma with low-grade dysplasia (p = 0.011) compared to normal specimens." (PMID 35047074, 2021). "The current study demonstrated a significant increase in CTLA-4 epithelial expression in adenoma with low-grade dysplasia, high-grade dysplasia and adenocarcinoma compared to normal specimens (p ˂ 0.001)." (PMID 35047074, 2021). "High CTLA-4+ TILs expression was in favour of adenoma with low-grade dysplasia when compared to adenoma with high-grade dysplasia and adenocarcinoma cases." (PMID 35047074, 2021). "The data from our systematic review showed a notable rise in CTLA-4 epithelial expression in adenomas with LGD, HGD, and CRC when compared to normal specimens, whereas the abundance of CTLA-4+ TILs significantly favored adenomas with LGD over normal mucosa, HGD, and adenocarcinoma cases." (PMID 40149674, 2025). "All the patients with adenoma received combination therapy with PD-1/L1 and CTLA-4 inhibitors." (PMID 37779873, 2023). "However, high CTLA-4+ TILs was significantly in favour of adenoma with low-grade dysplasia compared to normal specimens (p value = 0.001), high-grade dysplasia (p = 0.003) and adenocarcinoma cases (p = 0.019)." (PMID 35047074, 2021).
alopecia areata (5 papers, 2011 to 2024). Loss of scalp and body hair involving microscopically inflammatory patchy areas. "Conversely, alopecia areata is linked to CTLA‐4 gene variants, while CTLA‐4 IgG supplementation can avert its development in mice." (PMID 38451000, 2024). "The present study evaluated the potential association of two CTLA4 gene variants with alopecia areata in a Mexican population." (PMID 32278632, 2020). "Association between genes PTPN22, FAS/FASL and CTLA4 with alopecia areata." (PMID 34735462, 2021). "The genetic variants rs231775 and rs3087243 of the CTLA4 gene are not a risk factor for the development of alopecia areata in the analyzed Mexican population." (PMID 32278632, 2020).
Arrhythmia (5 papers, 2022 to 2025). Any cardiac rhythm other than the normal sinus rhythm. "This study showed that ICI-associated arrhythmias were over-reported for anti-PD-1/PD-L1 vs anti-CTLA-4 monotherapy [ROR: 1.80 (1.44–2.26) and 2.22 (1.76–2.80), respectively]." (PMID 36408225, 2022). "A comprehensive analysis of the FDA Adverse Event Reporting System highlighted that cardiac arrhythmias are a significant concern with ICIs, with anti-PD-1 and anti-PD-L1 therapies being associated with higher reports of arrhythmias compared to anti-CTLA-4 therapies." (PMID 40673965, 2025). "Due to the lack of researches on immunotherapy‐induced arrhythmia, it is necessary to explore and clarify the relationship between anti‐CTLA‐4 drugs and arrhythmia." (PMID 36426382, 2023). "Anti-PD-1 and anti-PD-L1 monotherapies were found to be related to higher reporting of arrhythmias, corresponding to ROR025 = 1.03, IC025 = 0.06 and ROR025 = 1.27, IC025 = 0.29, respectively, with the exception of anti-CTLA-4 monotherapies (ROR025 = 0.57, IC025 = −1.21)." (PMID 36408225, 2022). "Owing to a lack of studies on immunotherapy-induced arrhythmias, the rationale for no signal for anti-CTLA-4 drugs need to be further elucidated and explored." (PMID 36408225, 2022). "Concerning reports of cardiac arrhythmias, a significant increased ROR was found for anti-PD-1 monotherapy [ROR 1.11 (1.03–1.21), IC025 0.06] and anti-PD-L1 monotherapy [ROR 1.37 (1.27–1.49), IC025 0.29], with the exception of anti-CTLA-4 monotherapy [ROR 0.62 (0.57–0.67), IC025 −1.21]." (PMID 36408225, 2022).
cardiomyopathy (5 papers, 2012 to 2022). A disease of the heart muscle or myocardium proper. "We next aimed to study if the reduced frequency of CD4+CD25+ T cell expressing CTLA-4 and Foxp3 that we found in severe cardiomyopathy patients correlated with deficient regulatory activities." (PMID 22545173, 2012). "High percentage of CD4+CD25+Low T cells expressing Foxp3 (P = 0.016) and CTLA-4 (P = 0.046) were also observed in free/mild cardiomyopathy patients compared with moderate severe cardiomyopathy patients." (PMID 22545173, 2012). "Free/mild cardiomyopathy patients presented higher frequency of CD4+CD25high T cells expressing Foxp3 (P = 0.033) and CTLA-4 (P = 0.042) than moderate/severe cardiomyopathy patients." (PMID 22545173, 2012). "Nevertheless, it was previously reported that cardiomyopathy patients exhibit a higher percentage of CD4+CD25high T cells expressing CTLA-4." (PMID 22545173, 2012). "The impairment in suppressive activity observed in CD4+CD25+ T cells from patients suffering from severe cardiomyopathy correlates with the observation of reduced amounts of CD4+CD25+ T cells expressing CTLA-4 and Foxp3 in this group of patients." (PMID 22545173, 2012). "Lastly, we evaluated the expression of CTLA-4 in relation to the level of inflammatory mononuclear cells in heart tissue sections (i.e. heart explants) from T. cruzi infected subjects with severe cardiomyopathy who had undergone heart transplantation." (PMID 22574131, 2012). "Furthermore, the greater number of CD4+CD25− T cells of free/mild cardiomyopathy patients and Bz treated patients expressing CTLA-4 than cells from moderate/severe cardiomyopathy patients, probably contributes to the modulation of immune response in the heart." (PMID 22545173, 2012). "Moreover, the analysis of CD4+CD25Low cells population demonstrated that free/mild cardiomyopathy patients and Bz treated patients have a higher occurrence of CTLA-4 than moderate/severe cardiomyopathy patients." (PMID 22545173, 2012). "A higher expression of CTLA-4 and Foxp3 in the CD4+CD25high T cells from free/mild cardiomyopathy patients was observed, when compared to moderate/severe cardiomyopathy patients." (PMID 22545173, 2012). "The mechanism leading to reduced expression of Foxp3 and CTLA-4 and consequently, deficient suppressive activity of CD4+CD25+ T cells from patients with cardiomyopathy has not been elucidated." (PMID 22545173, 2012). "The high amount of CD4+CD25+ T cells expressing CTLA-4 and Foxp3 (that activate the regulatory T cell machinery) in CD4+ CD25+ T cells of free/mild cardiomyopathy and Bz treated patients may be related to high suppressor activity of these cells." (PMID 22545173, 2012). "Interestingly, the expression of CTLA-4, but not CD103, GITR and Foxp3, in CD4+CD25high T cells was decreased in moderate/severe cardiomyopathy compared with free/mild cardiomyopathy patients and health individuals." (PMID 22545173, 2012).
chronic hepatitis B (5 papers, 2015 to 2024). "There is an association between CTLA-4 -1661G>A gene polymorphism with HBV DNA suppression in chronic hepatitis B patients with TDF." (PMID 37767077, 2022). "Diagnostic accuracy of CTLA-4 in predicting HBV DNA suppression in chronic hepatitis B patients with TDF." (PMID 37767077, 2022). "The results showed the factors affecting HBV DNA suppression in chronic hepatitis B patients with tenofovir disoproxil fumarate (TDF) were the levels of CTLA-4, HBV DNA, ALT, and CTLA-4-1661G>A polymorphism." (PMID 37767077, 2022). "Possible underlying factors are as follows, on the one hand, prior researches have demonstrated that upregulation of regulatory factors such as PD‐1, CTLA‐4, and TIM‐3 serves as a significant mechanism of immune dysfunction induced by chronic hepatitis B virus infection." (PMID 38196277, 2024). "Patients with chronic hepatitis B (CHB) gradually develop T cell exhaustion, and the inhibitory receptor molecule, cytotoxic T-lymphocyte antigen-4 (CTLA-4), may play a role in this phenomenon." (PMID 37243227, 2023). "Differences in CTLA-4 levels between chronic hepatitis B patients who achieve and do not achieve HBV DNA suppression." (PMID 37767077, 2022).
Cirrhosis (5 papers, 2020 to 2025). A chronic disorder of the liver in which liver tissue becomes scarred and is partially replaced by regenerative nodules and fibrotic tissue resulting in loss of liver function. "Lower levels of CTLA-4 mRNA copies were related to the immune suppression caused by cirrhosis." (PMID 37325634, 2023). "A reasonable explanation for the reduced number of CTLA-4 mRNA copies is the immune suppression caused by cirrhosis; in others words, a longer disease may cause a downregulation of CTLA-4 expression." (PMID 32545568, 2020). "If both the SNP variants are present, patients not only have a reduced number of CTLA-4 mRNA copies, but also have cirrhosis more often and course of GGT tends to be worse independent from previous disease length." (PMID 32545568, 2020). "PBC patients with a low number of CTLA-4 copies showed cirrhosis more often (low: n = 9/30 vs. high 2/19, p = 0.02) and weaker recovery of GGT in course of their disease, defined as difference between initial diagnosis and the most current values." (PMID 32545568, 2020). "We could determine a significant correlation between number of CTLA-4 copies, cirrhosis, and course of GGT in time between inclusion and diagnosis, maybe in context of disease length." (PMID 32545568, 2020). "Moreover, the number of CTLA-4 copies was found to be positively correlated with inducible co-stimulator (ICOS) and FoxP3 expressions in PBC patients; lower number of CTLA-4 copies was associated with cirrhosis and decreased expression of CTLA-4 in late stage PBC." (PMID 37325634, 2023). "Therefore, the more intriguing explanation is, that the more frequent presence of cirrhosis and worse course of GGT is being caused by the low number of CTLA-4 copies, as the immune system lacks CTLA4-transmitted inhibition and might attack the bile ducts more fiercely." (PMID 32545568, 2020).
diarrhoea (5 papers, 2019 to 2025). "Diarrhoea was more frequently recorded in patients receiving anti-PD-1 and anti-CTLA-4 therapy." (PMID 39588146, 2024).
follicular lymphoma (5 papers, 2016 to 2025). Follicular lymphoma is a form of non-Hodgkin lymphoma characterized by a proliferation of B cells whose nodular structure of follicular architecture is preserved. "The majority of CTLA4 A17hom carriers had an indolent follicular lymphoma transformed to DLBCL, while the majority of T17hom carriers had de novo DLBCL." (PMID 40862794, 2025). "We identify several molecules that could contribute to the observed increased suppressive capacity of follicular lymphoma nodal tregs, including upregulation of CTLA-4, IL-10, and GITR, all confirmed by protein expression." (PMID 27228053, 2016).